CXCL5 (C-X-C motif chemokine ligand 5)
Diseases named in the same sentence as CXCL5 in open-access papers (continued):
Sharing a sentence is not in itself a finding about the gene and the disease.
influenza (7 papers, 2014 to 2024). An acute viral infection of the respiratory tract, occurring in isolated cases, in epidemics, or in pandemics; it is caused by serologically different strains of viruses (influenzaviruses) designated A, B, and C, has a 3-day incubation period, and usually lasts for 3 to 10 days. "Together, the data suggest that CXCL5 deficiency induced CXCL13 expression in pulmonary CD64+ macrophages/monocytes in influenza-infected lungs beginning in the early innate immunity stage." (PMID 34868067, 2021). "Considering abundant expression of CXCL5 in the infected lung during early influenza infection stage, CXCL5 deficiency might down-regulate CXCR2 axis in lung epithelial cells and lead to reduced CXCL1/2 expression form the cells which in turn decreasing neutrophil infiltration." (PMID 34868067, 2021). "Together, the results demonstrated that after recovery, both H1N1-infected WT and CXCL5-/- mice acquired potent adaptive immunity against infection with the same influenza strain or a different influenza strain (H3N2)." (PMID 34868067, 2021). "The finding that loss of CXCL5 signaling triggers CXCL13 expression in CD64+ macrophages/monocytes in influenza-infected mouse lungs suggests that CXCL5 negatively regulates CXCL13 expression in macrophages." (PMID 34868067, 2021). "The findings suggest that macrophages are the key leukocytes in the pathway by which CXCL5 controls CXCL13 expression during influenza infection." (PMID 34868067, 2021). "Further in vitro studies demonstrated that influenza virus infection induced CXCL13 expression in AMs and that CXCL5 administration inhibited CXCL13 expression in influenza-infected AMs." (PMID 34868067, 2021). "The results indicated that increased B cell accumulation occurred in the infected lungs of CXCL5-/- mice after influenza infection (3-8 d.p.i)." (PMID 34868067, 2021). "While neutrophil influx into infected lungs was increased in the E. coli-infected CXCL5-/- mouse model, the data suggest that it was decreased in the influenza-infected CXCL5-/- mouse model during the early innate immunity stage." (PMID 34868067, 2021). "Expression of the main neutrophil chemoattractants CXCL1, CXCL2, and CXCL5 were induced upon influenza infection, but were unaffected by IL-1β." (PMID 24918427, 2014). "Moreover, influenza-infected WT mice were intratracheally administered recombinant CXCL5 protein 5-8 d.p.i." (PMID 34868067, 2021). "Furthermore, the levels of CXCL13 in the culture supernatants of influenza-infected macrophages were significantly decreased upon the addition of recombinant CXCL5, recombinant CXCL1 and CXCL2, or all the proteins combined." (PMID 34868067, 2021). "Here, using an influenza (H1N1) infected CXCL5-/- mouse model, we found that CXCL5 not only responds to neutrophil infiltration into infected lungs at the innate immunity stage, but also affects B lymphocyte accumulation in the lungs by regulating the expression of the B cell chemokine CXCL13." (PMID 34868067, 2021). "In addition to production by structural cells, large amounts of CXCL5 production by blood hematopoietic cells were observed upon influenza infection." (PMID 34868067, 2021). "In contrast to the findings obtained with the bacterial infection model, those obtained with the influenza-infected CXCL5-/- mice indicated that the levels of the major neutrophil chemoattractants CXCL1 and CXCL2 in the lungs were significantly decreased during the early infection stage." (PMID 34868067, 2021). "Inhibition of CXCL5-CXCR2 axis markedly induces CXCL13 expression in CD64+CD44hiCD274hi macrophages/monocytes in infected lungs, and in vitro administration of CXCL5 to CD64+ alveolar macrophages suppresses CXCL13 expression via the CXCL5-CXCR2 axis upon influenza challenge." (PMID 34868067, 2021). "In influenza-inoculated mice, several chemokines, including CCL6, CCL17, CCL25, CCL28, and C-X-C motif chemokine 5 (CXCL5), increased, while CCL27a and CX3CL1 decreased." (PMID 35326323, 2022).
influenza (continued). "CXCL1 and CXCL2 expression was also induced in influenza-infected AMs; however, CXCL5 expression was not induced based on the detection of both mRNA and protein levels." (PMID 34868067, 2021). "Influenza infection induces pulmonary CXCL13 expression by type I IFN-activated lung fibroblasts; however, the levels of pulmonary IFN-α/β were comparable between WT and CXCL5-/- infected mice." (PMID 34868067, 2021). "Similarly, CCL2 (Ccl2), a ligand for CCR2 that recruits CCR2+ inflammatory monocytes, as well as CXCL1 (Cxcl1), CXCL2 (Cxcl2), and CXCL5 (Cxcl5), which are ligands of CXCR2 that induce neutrophil infiltration in influenza-infected lungs, showed notable decreases in NOD.SCID mice." (PMID 37904257, 2023). "In addition to regulating neutrophil chemokine levels in the influenza infection mouse model, CXCL5 has also been found to regulate the expression of another chemokine, CXCL13, a predominant B cell chemoattractant, in infected lungs after influenza infection." (PMID 34868067, 2021). "An influenza hemagglutination inhibition assay revealed that total H1N1-specific antibody levels in lung BALF but not in circulating system were significantly higher in CXCL5-/- mice than in WT mice at 8 d.p.i." (PMID 34868067, 2021). "In contrast, the expression of CXCL13 increased markedly in the group treated with CXCL5 and CXCR2 antagonists compared to the group without the CXCR2 antagonist upon influenza challenge." (PMID 34868067, 2021).
osteosarcoma (7 papers, 2012 to 2025). A usually aggressive malignant bone-forming mesenchymal neoplasm, predominantly affecting adolescents and young adults. "Osteosarcoma had 25 significant relationships, notably including IL-4/IL-1β (r2 = 0.58, p = 0.000048), IL-12 p40/IL-4 (r2 = 0.47, p = 0.0015), CXCL5/IL-27 (r2 = −0.48, p = 0.001), CXCL14/IL-15 (r2 = 0.66, p = 0.0000021)." (PMID 41008853, 2025). "The group with the worst EFS and OS for osteosarcoma and Ewing sarcoma, Group 1, was defined by an increase in CXCL5, CXCL12, and MIF." (PMID 41008853, 2025). "The frequent hyper-methylation and under-expression of CXCL5 were validated in five of the cell lines and five osteosarcoma tumour samples using methylation-specific PCR and quantitative real-time RT-PCR, respectively." (PMID 23144859, 2012). "MEST and CXCL5 were also shown to be under-expressed in 29/29 osteosarcoma clinical samples, respectively, whereas NNAT was under-expressed in 27/29 samples, based on identical types of microarray data (no methylation data was available)." (PMID 23144859, 2012). "Methylation-specific PCR and quantitative real-time RT-PCR were used to validate the promoter methylation status and the expression level of CXCL5, respectively, in five of the cell lines and five osteosarcoma tumour samples." (PMID 23144859, 2012). "Similarly, elevated levels of individual cytokines and chemokines, including IL-24, CXCL5, and CXCL10, were associated with inferior event-free or overall survival in patients with osteosarcoma." (PMID 41008853, 2025). "More interesting, we found many immune-related genes (including CCL3, CCL4, CCL4L2, and CXCL5) enriched in the thrombus samples of osteosarcoma, which indicates that multiple genes involved in immunological pathways may be activated concordantly." (PMID 37244923, 2023). "To determine whether CUL4B is specifically regulated by NF‐κB in osteosarcoma cells, we selected IL‐6, CXCL5, and CCR5 as representatives to monitor their expression in U2OS, MG63, Saos‐2, and HOS cells." (PMID 29377600, 2018). "Our results indicated that the expression of IL‐6, CXCL5, and CCR5 in osteosarcoma cells was similar to their levels in hFOB1.19 cells." (PMID 29377600, 2018). "Patients with osteosarcoma showing high CXCL5 had poorer OS (p = 0.010), but not EFS." (PMID 41008853, 2025).
pneumonia (7 papers, 2013 to 2025). An acute, acute and chronic, or chronic inflammation focally or diffusely affecting the lung parenchyma, caused by an infection in one or both of the lungs (by bacteria, viruses, fungi, or mycoplasma.). "However, CXCL5 deficiency during E. coli pneumonia increases neutrophil influx in the lungs, accelerates the pathogen clearance, improves pulmonary edema, and protects the mice from severe pneumonia and, thus, the ALI." (PMID 32849610, 2020). "The CXCL1 regulates neutrophil infiltration and the bacterial clearance during K. pneumoniae-induced pneumonia via regulating the CXCL2/MIP-2 and CXCL5, and NF-κB and MAPKs activation in the lungs." (PMID 32849610, 2020). "In the absence of CXCL5, CXCL1, and CXCL2 bind to the Duffy Antigen Receptor for Chemokines (DARC) to increase the neutrophil infiltration in the lungs, which enhances bacterial clearance, and protects the animal from severe pneumonia." (PMID 32849610, 2020). "CXCL5−/− mice do not show much decrease in CXCR2 expression on bone marrow and blood neutrophils as compared to the wild type (WT) mice upon E. coli-induced pneumonia, but the CXCR2 expression on neutrophils remains unchanged during intranasal lipopolysaccharide (LPS) challenge." (PMID 32849610, 2020).
Crohn disease (6 papers, 2019 to 2024). A gastrointestinal disorder characterized by chronic inflammation involving all layers of the intestinal wall, noncaseating granulomas affecting the intestinal wall and regional lymph nodes, and transmural fibrosis. "Ulcerative colitis is a sub type of IBD and CXCL5 have previously been shown to play a role in IBDs, such as ulcerative colitis and Crohn’s disease." (PMID 31727947, 2019). "Similarly, Cxcl9 expression is up-regulated in UC, and Cxcl5 is one of the main chemokines expressed in intestinal tissue of Crohn’s disease patients." (PMID 33864170, 2021). "In our exploration of the expression of angiogenesis-related genes in Crohn’s disease patients, we found upregulation of OSM, CXCL5, CEACAM3, ISG20, and DUOXA1 genes in Crohn’s disease patients." (PMID 38343536, 2024). "In SAM enteropathy and in Crohn's disease there was increased expression of DUOX2, DUOXA2, lipocalin 2, CEACAM 5 and 7, MUC1, SAA 1, 2 and 4, and CXCL5 genes, and these transcripts were further over-expressed in HIV infection." (PMID 31229436, 2019).
endometriosis (6 papers, 2013 to 2023). The growth of functional endometrial tissue in anatomic sites outside the uterine body. "Notably, innate cellular chemoattractants (IL-12, I-309/CCL1, Eotaxin, MCP-1, IL-6, IL-8, and IFN-γ) were almost exclusively elevated in endometriosis patients with the sole exception of the neutrophil chemoattractant ENA-78/CXCL5." (PMID 31333337, 2019).
esophageal cancer (6 papers, 2017 to 2023). A primary or metastatic malignant neoplasm involving the esophagus. "In this work, lymph node metastasis in skin cutaneous melanoma was associated with CXCL2, in liver hepatocellular carcinoma with CXCL5, in kidney renal clear cell carcinoma with PPBP, and in esophageal carcinoma with CXCL8/IL-8." (PMID 37686093, 2023). "The significance of CXCL5 in oesophageal cancer has not been reported." (PMID 28186102, 2017). "Similar correlations were observed in esophageal carcinoma, with CXCL1, CXCL2, CXCL3, and PPBP negatively correlated with EMT, CXCL5 and CXCL6 positively correlated with EMT, and CXCL8 not correlated with EMT." (PMID 37686093, 2023).
glioblastoma (6 papers, 2020 to 2025). The most malignant astrocytic tumor (WHO grade IV). "For example, increased expression of CXCL5 in the tumor microenvironment has been linked to activation of the CXCR2 pathway and recruitment of pro-tumor immune cells, thereby promoting tumorigenesis and angiogenesis, demonstrating that CXCL5 expression drives glioblastoma progression." (PMID 41387890, 2025). "Genes that show higher expression in astrocytoma compared to glioblastoma were CX3CL1, CSF1 (MCSF), CCL3 (MIP1α), CCL4 (MIP1β), TGFα, FLT3LG, CXCL5, CCL19 while KITLG (SCF) and NGF were equally expressed in the two tumor types." (PMID 35301393, 2022). "Our study shows the cells grown in 3D-GMH with serum overexpress and secrete CXCL1, CXCL5, IGFBP2, PTX3, THBS1, VEGFA, and VCAM1—all genes expressed in perivascular or perinecrotic zone of glioblastoma tissues that are hotspots for immune cells." (PMID 34489494, 2021). "Notably, both CXCL3 and CXCL5 were identified as hub genes, indicating the significant involvement of the CXCR2 signaling pathway in the progression of glioblastoma." (PMID 38365809, 2024).
head and neck squamous cell carcinoma (6 papers, 2013 to 2025). A squamous cell carcinoma that arises from any of the following anatomic sites: lip and oral cavity, nasal cavity, paranasal sinuses, pharynx, larynx, and salivary glands. "The level of CXCL5 in LN metastasis was significantly higher than that in primary head and neck squamous cell carcinoma." (PMID 35504887, 2022). "CXCL5 is required for cell proliferation of head and neck squamous cell carcinoma." (PMID 26248031, 2015). "Targeting six immune-related genes (CXCL5, ADM, FGF9, AIMP1, STC1, and CDKN2A) in individuals diagnosed with head and neck squamous cell carcinoma has shown promising results in immunotherapy triggered by periodontal disease." (PMID 37675228, 2023).
lung adenocarcinoma (6 papers, 2012 to 2026). A carcinoma that arises from the lung and is characterized by the presence of malignant glandular epithelial cells. "In contrast to lung adenocarcinoma, survival analysis of the TCGA lung squamous cell carcinoma (LUSC) dataset revealed that the expression levels of BIRC3, CXCL5, DKK1, FOSL1, and MYC exhibited limited association with patient survival." (PMID 39858622, 2025). "We further analyzed mRNA profiles in another dataset with 439 lung adenocarcinomas, the patients were arbitrarily separated into three groups according to high, midium or low expression of CXCL5." (PMID 25788272, 2015). "Tumour-specific methylation of CXCL5 has also been observed in 80% of primary lung adenocarcinomas and 65% of lung adenocarcinoma cell lines, and demethylation using 5-Aza-2′-deoxycytidine also restored the expression of CXCL5." (PMID 23144859, 2012). "To explore the potential value of CXCL5 expression as a biomarker in NSCLC, we analyzed GEO dataset GSE31210, which include 226 cases of pathological stage I-II lung adenocarcinomas with survival follow-up." (PMID 25788272, 2015). "The role of CXCL5/CXCR2 on tumor cells themselves has been less studied, but a recent study suggests an important role of CXCL5 in lung adenocarcinomas in promoting invasion and metastasis." (PMID 25076207, 2014). "The expression level of CXCL5 was not correlated with patient survival in the TCGA lung adenocarcinoma database." (PMID 39858622, 2025). "We also found the substantial expression of several chemokines (CXCL1, CXCL5, CXCL8, and CX3CL1) related to cell migration, invasion, metastasis, or EMT, in KRAS-mutant lung adenocarcinoma cell lines, which was also dependent on MAPK signaling (unpublished data)." (PMID 27846317, 2016).
lung disease (6 papers, 2015 to 2025). "Overstimulation of these chemokines, particularly CXCL5, is known to cause destructive inflammatory lung conditions in specific pathogenic models of lung disease." (PMID 34786557, 2020). "Most of the selected biomarkers increased with severity of lung disease, except CXCL5 which was lower in those with more severe airflow obstruction." (PMID 30563576, 2018).
lymph node metastasis (6 papers, 2013 to 2024). "In particular, patients with high expression levels of CXCL5 are more likely to have lymph node metastasis, a higher tumor stage, and shorter overall survival (OS) and progression-free survival (PFS)." (PMID 36612163, 2022).
multiple sclerosis (6 papers, 2016 to 2024). A progressive autoimmune disorder affecting the central nervous system resulting in demyelination. "CXCL5 has also been identified as a potential serum biomarker for white matter lesions in preterm infants, glial hyperplasia in Alzheimer’s disease and multiple sclerosis (MS)." (PMID 38271077, 2024). "Chemokines (C-X-C) motif ligand (CXCL) 5 and 8 are overexpressed in patients with multiple sclerosis, where CXCL5 serum levels were shown to correlate with blood–brain barrier dysfunction as evidenced by gadolinium-enhanced magnetic resonance imaging." (PMID 30704100, 2019).
type 2 diabetes (6 papers, 2009 to 2024). "Among them, Cxcl1 and Cxcl5 have been found to be altered in the serum of patients with type 2 diabetes." (PMID 25073444, 2014). "Under the metabolic environment of type 2 diabetes mellitus (T2DM), activated platelets can release chemokines such as CXCL4, CXCL5, and CCL5 on vascular cell surfaces, triggering atherogenesis." (PMID 34357044, 2021). "Accordingly, in line with our in vitro findings on EPCs from type 2 diabetic patients, our in vivo findings suggested that CXCL5 was not just an indicator, which might impair rather than promote angiogenesis as well as wound healing in diabetic animals." (PMID 37420254, 2023). "However, the findings of our in vitro study did indicate the beneficial effects of direct CXCL5 inhibition on EPCs from type 2 diabetic patients and that on HG-treated EPCs from non-DM subjects." (PMID 37420254, 2023).
ulcerative colitis (6 papers, 2014 to 2024). An inflammatory bowel disease involving the mucosal surface of the large intestine and rectum. "MR implicated CXCL5 in the etiology of ulcerative colitis (UC) and we show elevated gut CXCL5 transcript expression in patients with UC." (PMID 37563310, 2023). "DNA hypermethylation in the promoters of CXCL14, CXCL5, GATA3, IL17C, and IL4R and hypomethylation in the promoters of CCL25, IL13, IL12B, CXCL5, IL4R, IL17A, and IL17RA are associated with the onset or aggravation of ulcerative colitis." (PMID 38473997, 2024). "For example, the top variants for CXCL5 found in this study (rs352045 in ONC_CVD and rs425535 in INF) are both in high LD (R2 = 0.944) with a variant previously associated with ulcerative colitis." (PMID 31727947, 2019). "In ulcerative colitis (UC) 5 genes (CXCL14, CXCL5, GATA3, IL17C, and IL4R) were hypermethylated compared to healthy controls." (PMID 25526479, 2014).
liver fibrosis (5 papers, 2021 to 2025). "A role of MALAT1 in liver fibrosis via the regulation of the chemokine CXCL5 was also reported in a study investigating fibrosis in NASH patients." (PMID 40002783, 2025). "Another study on nonalcoholic steatohepatitis fibrosis showed that MALAT1 plays a key role in liver fibrosis by regulating the chemokine CXCL5." (PMID 35769097, 2022). "In liver fibrosis, numerous lncRNAs such as MALAT1, LFAR1, H19, and NEAT1 was implicated in various inflammatory chemokine pathways including transforming growth factor β (TGF-β), activation of macrophage, and C-X-C motif chemokine ligand 5 (CXCL5)." (PMID 34938356, 2021).
myeloma (5 papers, 2013 to 2025). "Serum concentrations of CXCL1 and CXCL5 in myeloma patients were below the concentrations used in our in vitro studies (186.5 ± 129.1 pg/ml and 765 572.1 pg/ml, respectively)." (PMID 25268740, 2014). "When we tested the putative angiogenic potential of the three chemokines, an increasing dose-response in the tubule formation assay was found for CXCL1 and CXCL5, even at lower concentrations than those required to induce myeloma growth." (PMID 25268740, 2014). "It has previously been shown that IL-27 has anti-angiogenic activity by down regulating the expression of VEGF, IL-8/CXCL8 and CXCL5 in human multiple myeloma cells." (PMID 24274066, 2013).